RBBP8NL (RBBP8 N-terminal like)
Synonyms: C20orf151; dJ908M14.3
Tractability: PROTAC: ubiquitination databases record sites on it.
Gene: Protein-coding gene on chromosome 20 (62,410,237 to 62,427,539, reverse strand). Ensembl gene ENSG00000130701.
Subcellular location (Human Protein Atlas): Nucleoplasm; Vesicles
Gene Ontology:
Molecular function: protein binding
Cellular component: extracellular region
Genetic constraint (gnomAD): Loss-of-function variants: 59 observed, 48.2 expected, observed/expected ratio (o/e) 1.22, 90% interval 0.99 to 1.52. The synonymous counts are far from expectation, so gnomAD's model fits this gene poorly and the ratio says little. Missense variants: 896 observed, 738.13 expected, observed/expected ratio (o/e) 1.21, 90% interval 1.15 to 1.28. Synonymous variants: 411 observed, 318.6 expected, observed/expected ratio (o/e) 1.29, 90% interval 1.19 to 1.4.
Homologues: Orthologues: chimpanzee RBBP8NL (98% identical), macaque RBBP8NL (90% identical), dog RBBP8NL (67% identical), guinea pig RBBP8NL (61% identical), rat Rbbp8nl (59% identical), mouse Rbbp8nl (57% identical), pig RBBP8NL (57% identical), tropical clawed frog rbbp8nl (29% identical), zebrafish rbbp8l (21% identical), Caenorhabditis elegans com-1 (11% identical). Paralogues in human: RBBP8 (23% identical).
Diseases named in the same sentence as RBBP8NL in open-access papers:
RBBP8NL is named in the same sentence as 1 disease in open-access papers, as found by Europe PMC text mining. Sharing a sentence is not in itself a finding about the gene and the disease.
RBBP8NL shares sentences with these, for which no sentence is quoted: tumor (1 paper).